SETD2 (SET domain containing 2, histone lysine methyltransferase)
Diseases named in the same sentence as SETD2 in open-access papers (continued):
Sharing a sentence is not in itself a finding about the gene and the disease.
renal cell carcinoma (31 papers, 2015 to 2025). "When comparing the differences across cancer types, our results showed that a more inflamed tumor microenvironment was present in the SETD2 deleterious mutation group in colorectal carcinoma, endometrial carcinoma, and renal cell carcinoma." (PMID 37479966, 2023). "This revealed that a SETD2 deleterious mutation was associated with a more inflamed tumor microenvironment in patients with renal cell carcinoma, colorectal adenocarcinoma, and endometrial carcinoma." (PMID 37479966, 2023). "In contrast, studies have indicated that bi-allelic loss of SETD2 is needed to significantly decrease levels of H3K36me3 in in vitro models and renal cell carcinoma." (PMID 30419952, 2018). "NSD1 is a histone 3 Lys 36 (H3K36) methyltransferase similar to SETD2, which is frequently mutated in the clear cell variant of renal cell carcinoma, and associated with DNA hypomethylation." (PMID 28405244, 2017). "A number of studies have reported that variants in somatic SETD2 gene are related to the occurrence of a variety of tumors, especially renal cell carcinoma, pulmonary adenocarcinoma, enteropathy-associated T cell lymphoma, chronic lymphocytic leukemia, and gastrointestinal stromal tumors." (PMID 36777730, 2023). "Notably, mutations in SETD2, an RNA polymerase II–associated histone methyltransferase known to promote metastasis in multiple cancers including renal cell carcinoma, were markedly more frequent in the high-risk group (14%) compared with the low-risk group (< 4%)." (PMID 41013841, 2025). "There was also a higher immune score in the SETD2 mut + group in colorectal adenocarcinoma, renal cell carcinoma, and endometrial carcinoma." (PMID 37479966, 2023). "The mutation rate of VHL in renal cell carcinoma was the highest, followed by PBRM1, TTN, and SETD2." (PMID 36186476, 2022). "Copy number losses were also identified in DLG2 (8% WGS samples), SETD2 (4% WGS), and DMD (29% WGS), genes previously associated with other human cancers such as OS, renal cell carcinoma and myogenic sarcomas." (PMID 31341965, 2019). "Remarkably, inactivation of SETD2 has been found in cell lines of ccRCC and clinical samples in which SETD2 has been demonstrated to function as a tumor suppressor gene in renal cell carcinoma." (PMID 25714014, 2015). "We then studied the tissue specificity of TGX221 and found that only renal cell carcinoma harbours VHL and/or SETD2 mutations in GDSC database and TGX221 exhibited sensitivity for RCC cells with such mutations." (PMID 25853938, 2015). "SETD2 and VHL are both commonly mutated genes in renal cell cancer." (PMID 37933774, 2023). "Our results identify a highly conserved DNA hypermethylation phenotype induced by SETD2 inactivation that functionally modulates the gene expression program of renal cell cancers, suggesting that DNA demethylating agents represent a potential rational therapy to target SETD2 loss of function tumors." (PMID 26646321, 2016). "The impact of dysregulated SETD2 and, hence, H3K36me3 on AS transcripts has been further explored in renal cell carcinomas (RCC)." (PMID 35955433, 2022). "Similarly, H3K36M has not been reported in renal cell cancer where SETD2-inactivating mutations were identified." (PMID 30101054, 2018). "Interestingly, H3K36me3 depletion in SETD2-mutant renal cell carcinoma has been correlated with defects in transcriptional termination and readthrough into neighboring genes, suggesting that H3K36 methylation might influence termination and polyadenylation." (PMID 28346137, 2017). "Further statistical analysis revealed non-hotspot mutations within SETD2 with missense mutations predominating in NSCLC, melanoma, and colorectal cancer, whereas truncating mutations predominated in renal cell carcinoma." (PMID 37479966, 2023).
renal cell carcinoma (continued). "In renal cell carcinoma (RCC), for example, a panel of mRNA markers (CUL9, KMT2D, PBRM1, PREX2, and SETD2) has been identified as a highly accurate classifier, distinguishing RCC from benign renal masses with an AUC of 0.83." (PMID 40149276, 2025).
renal carcinoma (29 papers, 2012 to 2025). A carcinoma arising from the epithelium of the renal parenchyma or the renal pelvis. "Recent studies have unveiled that renal cancer cells harboring SETD2 mutations or downregulated SETD2 expression are highly sensitive to histone demethylase inhibitors (HDMIs) in both in vitro and in vivo models 76-77." (PMID 40959108, 2025). "RENOIR played a pivotal role in the development of a robust model for diagnosing SETD2-mutated renal cancers." (PMID 38253545, 2024). "In previous renal cancer studies, where SETD2 mutations have been associated with DNA methylation changes, the effect of co-occuring mutations has not been accounted for." (PMID 37528416, 2023). "Further, we develop a renal cancer signature of SETD2 loss using a unique machine-learning approach comprising multiple random sampling and repeated cross-validation, and successfully validated our biomarker in an independent Japanese renal cancer dataset." (PMID 37528416, 2023). "In renal cancer, SETD2 mutations are frequently associated with VHL, PBRM1, and BAP1 mutations as a result of chromosome 3p21 deletion." (PMID 37528416, 2023). "Deleterious mutations in SETD2 have been implicated in a wide range of solid tumors, including renal cancer, lung cancer, melanoma, gastrointestinal cancer, and endometrial cancer." (PMID 37479966, 2023). "Many tumors, including renal cancer, gastric cancer, lung cancer, are closely related to SETD2 gene mutations." (PMID 37359376, 2023). "In previous studies, SETD2 has been considered a tumor suppressor, and it has a high deletion mutation rate in renal cancer." (PMID 37604811, 2023). "33,153 differentially methylated CpGs were identified upon comparing SETD2 mutated and SETD2 control renal cancers (BH-adjusted p-value < 0.05), with 10,549 CpGs hypomethylated in SETD2 cases and 22,604 CpGs hypermethylated CpGs." (PMID 37528416, 2023). "Supporting this finding, studies have reported SETD2 mutations to be characteristic of a certain group of renal cancers associated with CIMP." (PMID 35134107, 2022). "It should be noted that, during the preparation of this paper, one study reported that the loss of SETD2 attenuated autophagy indirectly by targeting actin lysine 68 trimethylation in a human renal cancer cell line." (PMID 36359729, 2022). "SETD2 is frequently mutated in cancer; 4.33% of all cancers carry SETD2 mutations, with endometrial cancer, renal cancer, bladder cancer and colorectal cancer being most frequently associated with SETD2 mutations." (PMID 36052643, 2022). "For example, the SETD2 loss-of-function mutations were found in renal carcinoma, lung cancer, gastrointestinal cancer, and hematologic malignancies, indicating that SETD2 is a tumor suppressor." (PMID 32025281, 2020). "Great efforts of high-throughput sequencing have revealed that SETD2 is mutated or its function is lost in a range of solid cancers, including renal cancer, gastrointestinal cancer, lung cancer, pancreatic cancer, osteosarcoma, and so on." (PMID 32231741, 2020). "Notably, our tool identified a robust model for diagnosing SETD2-mutated renal cancers, exhibiting strong generalisation in an independent cohort." (PMID 38253545, 2024). "Loss of SETD2 has previously been shown to affect DNA methylation in renal cancer." (PMID 37528416, 2023). "Interestingly, EIF3D overexpression is a driver of sunitinib resistance in renal cancer and another study has shown that SETD2 mutations are associated with sunitinib resistance." (PMID 37528416, 2023). "In reality, mutations of different genes will have different consequences for fitness; for example, that distinct mutations of the SETD2 gene are found in different intratumour clones in the same renal carcinoma indicates a strong selective pressure for inactivation of this particular gene." (PMID 23396531, 2013).
renal carcinoma (continued). "RENOIR’s contribution enabled the identification of a 3-CpG model with an 89% accuracy in correctly classifying renal cancer samples as SETD2 cases or wild type (WT)." (PMID 38253545, 2024). "This was further confirmed as the most hypomethylated CpGs in renal cancer identified in our study mapped to genes that lost H3K36me3 in SETD2 knock-out renal carcinoma cell lines." (PMID 37528416, 2023). "Based on an analysis of 79 genes associated with renal cancer, we found that VHL, PBRM1, BAP1, SETD2, and TSC1 mutation rates were higher in all RCCs at 51%, 35%, 16%, 15%, and 13%, respectively." (PMID 37427096, 2023). "Subsequently, we examined the expression levels of SETD2 protein in several renal cancer cell lines (A498, ACHN, 786-O, and OS-RC-2), and its expression was consistent with H3K36me3." (PMID 37604811, 2023). "As reported in our review, the most common somatic gene mutations in renal cancer are related to VHL, PBRM1, BAP1, and SETD2, although a relatively small number of other mutated genes are reported to be involved in kidney cancer." (PMID 36902045, 2023). "Consistent with this, SETD2 depletion reduces replication fork speed in renal carcinoma cells and deletion of SetD2 leads to replication stress in mouse hematopoietic stem cells." (PMID 35661267, 2022). "Mechanically, SETD2 in renal cancer plays a role in epigenetic dysfunction and metabolism regulation." (PMID 32231741, 2020). "We detected a peak of homozygous deletions in lung cancer close to SETD1B, a member of a family of histone methyltransferases that also includes SETD2, known to be involved in renal carcinoma." (PMID 29089486, 2017). "We found that classic renal cancer–related genes such as VHL, PBRM1, TTN, and SETD2 had higher mutation frequencies in the TCGA-KIRC cohort, with PBRM1 having a higher mutation rate in XPS1 compared to XPS2 (43% vs. 37%), while mTOR had a lower mutation rate in XPS1 compared to XPS2 (6% vs. 10%)." (PMID 39882192, 2025). "SETD2, a histone methyltransferase, is recognized as a critical tumor suppressor in renal cancer." (PMID 41013841, 2025). "These were cg14297023, cg17054691, and cg25415966, and could correctly identify renal cancer samples as SETD2 cases or WT with a misclassification error of only 0.11." (PMID 37528416, 2023). "All of these studies have indicated that SETD2 acts as a tumor suppressor in renal cancer." (PMID 32231741, 2020). "SETD2 mutation fluently occurs in renal cancer 11, 58-62, and the absence of SETD2 protein is more evident than deficiency of the SETD2 gene itself." (PMID 32231741, 2020). "In addition to renal cancer, in pancreatic cancer cells, the deletion of SETD2 will promote the reorganization of acinar to ductal metaplasia (ADM) of pancreatic acinar cells driven by the oncogene KRAS, which is mainly mediated by F-box and WD repeat domain protein 7 (Fbxw7)." (PMID 40786181, 2025). "SETD2 modulates FECH expression via H3K36me3-mediated transcriptional regulation, influencing ferroptosis sensitivity in renal cancer cells." (PMID 41203594, 2025). "The expression of SETD2 and VHL is positively correlated in patients with renal fibrosis and renal cancer, indicating their clinical significance." (PMID 37933774, 2023). "This is similar to the distinct TMPRSS-ERG fusions identified in several regions of the primary prostate tumour and alterations of SETD2, PTEN and KDM5C in renal cancer." (PMID 28961847, 2017). "We also collected the renal cancer tissue that was assessed for the expression of classical onco‐suppressor genes, downregulated in RCC, namely von Hippel–Lindau (VHL) Polybromo‐1 (PBRM1), SETD2, and BAP1." (PMID 39806854, 2025). "However, the relationship between SETD2 and ferroptosis in renal cancer is not clear." (PMID 37604811, 2023).
lung carcinoma (26 papers, 2014 to 2025). "Understanding the differential expression of these markers would further elucidate the etiology of favorable outcomes in SETD2-mutated lung cancer." (PMID 41228333, 2025). "In lung cancer, inactivation of SETD2 and subsequent loss of H3K36me3 led to an acceleration of progression of both early and late-stage tumors." (PMID 39591760, 2025). "Of the 3078 cases of lung cancer diagnosed between 1 January 2015 and 4 January 2024, 229 (7.4%) were SETD2-mutated." (PMID 41228333, 2025). "SETD2 is an understudied gene that encodes for a histone methyltransferase implicated in lung cancer tumorigenesis." (PMID 41228333, 2025). "In lung cancer, mutations or deletions of SETD2 lead to decreased H3K36me3 levels, triggering replication stress, DNA mismatch repair defects, and genomic instability, thereby promoting tumor heterogeneity and drug resistance." (PMID 41394878, 2025). "Future larger and more granular study is warranted on both the outcomes and prognosis of patients with SETD2-mutated tumors as well as immunopathologic characteristics of SETD2-mutated lung cancer." (PMID 41228333, 2025). "Mutation of SETD2 gene or its functional loss in lung cancer 81-86 has a higher frequency in metastatic sites compared with primary sites, which is linked to poor prognosis 82,83." (PMID 32231741, 2020). "Interestingly, the potential favorable prognostic value of the SETD2 mutation in lung cancer differs from that described in clinical studies of other cancers." (PMID 41228333, 2025). "This may be due to improved sensitivity to available treatments—SETD2 mutation in lung cancer has been associated with an improved response to radio- and immunotherapy." (PMID 41228333, 2025). "However, pre-clinical models of lung cancer suggest that SETD2-mutated tumors are associated with rapid tumor growth, but a relatively lower likelihood of metastasis compared to other pre-clinical lung cancer models." (PMID 41228333, 2025). "Importantly, SETD2 loss sensitized KRAS-mutant lung cancer to inhibition of histone chaperones, the FACT complex, or transcriptional elongation both in vitro and in vivo." (PMID 36810256, 2023). "In addition, loss-of-function mutation in SETD2 and/or decreased H3K36me3 levels have been linked to poor clinical prognosis in lung cancer and ccRCC." (PMID 30922329, 2019). "Additionally, the paradoxical finding that pre-clinical data demonstrates pro-tumorigenic effects however clinical data thus far has consistently demonstrated more favorable outcomes underscores the need for further investigation into SETD2-mutated lung cancer." (PMID 41228333, 2025). "In addition, SETD2 is mutated in other cancer types, such as non‐small cell lung cancer, where VHL and PBRM1 mutations rarely occur, although this does not preclude the possibility that SETD2 cooperates with other mutated genes such as K‐RAS in context of lung cancer." (PMID 37418588, 2024). "Despite the implication of SETD2 inactivation in the growth of lung cancer, several studies have shown it is a potentially favorable prognostic factor." (PMID 41228333, 2025). "These functions, which would be expected to limit cellular proliferation, are consistent with the proliferation-driving effects of Setd2 inactivation in KRAS-driven lung cancer." (PMID 36899051, 2023). "To investigate the effect of SETD2 on phenotypes of lung cancer cells in vitro, we first ectopically overexpressed a wildtype or a catalytically dead version of SETD2 (F2478L mutant) in lung cancer cells H1650 and PC-9." (PMID 33223508, 2020).
lung carcinoma (continued). "Previous reports have identified that SETD2 deficiency is involved in resistance of chemotherapy drugs in solid tumors 68,72, and SETD2 also plays a key role in the treatment of lung cancer." (PMID 32231741, 2020). "To further investigate the negative regulation of SETD2 on CXCL1 in lung cancer, we examined the correlated expression between SETD2 and CXCL1." (PMID 33223508, 2020). "To further illustrate the critical role of SETD2 on proliferation of lung cancer cells in vitro, we next knock-downed the level of SETD2 in lung cancer cells H1650 and PC-9 via two lentivirus-mediated shRNAs (shRNA1 and shRNA2) targeting SETD2." (PMID 33223508, 2020). "Results indicated that the CXCL1 expression was down-regulated by SETD2 overexpression in lung cancer cells H1650 and PC-9, while SETD2 deletion up-regulated the expression of CXCL1 in these two cell lines." (PMID 33223508, 2020). "We find that the H3K36 trimethylase SETD2 and dimethylase NSD1 are among the top 25 most mutated chromatin factors in kidney, head and neck, and lung carcinoma." (PMID 25484917, 2014). "However, CREB1 phosphorylation contributes to cisplatin sensitivity in lung cancer cells via regulation of the ERK pathway, especially in cancer cells with mutated SET domain containing 2 (SETD2), a histone H3 lysine 36 (H3K36) trimethyltransferase." (PMID 38233872, 2024). "Likewise, human lung cancer cell lines (A549, H1975, H1299, H1650 and PC-9) showed a significantly lower expression of SETD2 compared with HBE cell line." (PMID 33223508, 2020). "Collectively, loss of SETD2-mediated H3K36me3 is associated with increased chromatin recruitment of histone chaperones ASF1A/B, enhanced histone exchange, and increased H3K56ac deposition in both kidney and lung cancers, all of which is analogous to the findings observed in Set2-deficient yeast." (PMID 36810256, 2023). "To interrogate how chromatin accessibility might affect Etv1 expression in lung cancer, we assessed the ATAC-Seq tracks at the Etv1 locus, which revealed significantly increased chromatin accessibility at both promoter and intron 4 upon SETD2 loss." (PMID 36810256, 2023). "In conclusion, SETD2 may function as a tumor suppressor gene in the development of lung cancer." (PMID 32231741, 2020). "In lung cancer, abnormal expression of multiple HMTs leads to disrupted methylation patterns, among which EZH2 and SETD2 are the most representative key regulators." (PMID 41394878, 2025). "Multiple under-expressed proteins were also predictable to a great extent, the top-performing ones being CASP8, MET, BCL2, and SETD2 in BRCA; AR and TFRC in gastric cancer; and VHL in lung cancer with AUCs ranging 0.814–0.866." (PMID 38491101, 2024). "Retroviral transduction of SETD2ΔN in both mouse KrasG12DSetd2–/– lung cancer cells and JHRCC12 kidney cancer cells downregulated RET, supporting a regulation of RET by SETD2 in both lung and kidney cancers." (PMID 36810256, 2023). "Meanwhile, the lung cancer cell lines (A549, H1975, H1299, H1650 and PC-9) showed a remarkably higher expression level of CXCL1 compared with HBE cell line, showing an opposite expression pattern of SETD2." (PMID 33223508, 2020).